NPIPB4 (nuclear pore complex interacting protein family member B4)
Synonyms: 61E3.4
Gene: Protein-coding gene on chromosome 16 (21,834,563 to 21,880,827, reverse strand). Ensembl gene ENSG00000185864.
Subcellular location: Membrane
Subcellular location (Human Protein Atlas): Nucleoplasm
Genetic constraint (gnomAD): Loss-of-function variants: 0 observed, 4.59 expected, observed/expected ratio (o/e) 0, 90% interval 0 to 0.65. That is too few expected variants to judge how well the gene tolerates losing a copy. Missense variants: 55 observed, 136.85 expected, observed/expected ratio (o/e) 0.4, 90% interval 0.32 to 0.5. Synonymous variants: 18 observed, 50.49 expected, observed/expected ratio (o/e) 0.36, 90% interval 0.25 to 0.53.
Homologues: Paralogues in human: NPIPB13 (92% identical), NPIPB5 (85% identical), NPIPB11 (84% identical), NPIPB12 (75% identical), NPIPB3 (34% identical), NPIPB8 (27% identical), NPIPB9 (27% identical), NPIPB6 (26% identical), NPIPB2 (25% identical), NPIPB15 (25% identical), NPIPB7 (24% identical), NPIPA2 (23% identical), and 7 more.
Diseases named in the same sentence as NPIPB4 in open-access papers:
NPIPB4 is named in the same sentence as 3 diseases in open-access papers, as found by Europe PMC text mining. Sharing a sentence is not in itself a finding about the gene and the disease. The quoted sentences say what the papers report.
oral cancer (1 paper, 2020). "This study provides novelty by showing that mRNA levels of MAOB, NAB2, COL3A1, NPIPB4, CYP27A1, and SIAE were significantly reduced in the saliva of oral cancer patients." (PMID 31963366, 2020).
tumor (2 papers, 2020 to 2025). "NAB2, CYP27A1, NPIPB4, MAOB, and SIAE, demonstrated lower expression for the OSCC group compared with a non-tumor group." (PMID 40723410, 2025). "MAOB, NPIPB4, CYP27A1, and SIAE showed significantly lower expression levels in OSCC tumor tissues compared to normal tissues." (PMID 31963366, 2020).
cancer (1 paper, 2025). A tumor composed of atypical neoplastic, often pleomorphic cells that invade other tissues. "Additional genes identified included GALNT10, NPIPB4, POGZ, MED13L and UGGT1, most of which had confirmed roles in cancers." (PMID 40507918, 2025).